RARS1 (arginyl-tRNA synthetase 1)
Description:
Forms part of a macromolecular complex that catalyzes the attachment of specific amino acids to cognate tRNAs during protein synthesis. Modulates the secretion of AIMP1 and may be involved in generation of the inflammatory cytokine EMAP2 from AIMP1.
Synonyms: ArgRS; RARS; DALRD1; HLD9
Tractability: Small molecule: a structure with a bound ligand is known. PROTAC: ubiquitination databases record sites on it; a small molecule that binds it is known.
Target class: Enzyme; Ligase
Gene: Protein-coding gene on chromosome 5 (168,486,447 to 168,519,306, forward strand). Ensembl gene ENSG00000113643.
Subcellular location: Cytoplasm; Cytoplasm, cytosol
Subcellular location (Human Protein Atlas): Cytosol; Nucleoli; Nucleoplasm
Pathways (Reactome):
Developmental Biology: Transcriptional and post-translational regulation of MITF-M expression and activity
Metabolism: Selenoamino acid metabolism
Metabolism of proteins: Cytosolic tRNA aminoacylation
Gene Ontology:
Molecular function: arginine-tRNA ligase activity; cadherin binding; protein binding; aminoacyl-tRNA ligase activity; arginine binding; ATP binding; nucleotide binding; tRNA binding
Biological process: arginyl-tRNA aminoacylation; translation; tRNA aminoacylation for protein translation
Cellular component: aminoacyl-tRNA synthetase multienzyme complex; cytoplasm; cytosol; extracellular exosome; membrane; nucleus
Genetic constraint (gnomAD): Loss-of-function variants: 55 observed, 63.79 expected, observed/expected ratio (o/e) 0.86, 90% interval 0.69 to 1.08. The upper end of that interval is the gene's LOEUF score, 1.08, which puts it in group 4 of 6, group 1 being the genes least tolerant of losing a copy. Missense variants: 680 observed, 713.96 expected, observed/expected ratio (o/e) 0.95, 90% interval 0.89 to 1.01. Synonymous variants: 242 observed, 242.93 expected, observed/expected ratio (o/e) 1, 90% interval 0.9 to 1.11.
Gene-disease validity (ClinGen):
ClinGen rates the evidence that RARS1 causes each of these diseases.
hypomyelinating leukodystrophy 9 (autosomal recessive): Definitive. Any leukodystrophy in which the cause of the disease is a mutation in the RARS gene.
Homologues: Orthologues: macaque RARS1 (98% identical), chimpanzee RARS1 (97% identical), dog RARS1 (93% identical), rabbit RARS1 (92% identical), mouse Rars1 (92% identical), rat Rars1 (92% identical), pig RARS1 (91% identical), guinea pig RARS1 (91% identical), zebrafish rars1 (77% identical), Drosophila melanogaster ArgRS (58% identical), Caenorhabditis elegans rars-1 (52% identical). Paralogues in human: RARS2 (24% identical).
Diseases named in the same sentence as RARS1 in open-access papers:
RARS1 is named in the same sentence as 27 diseases in open-access papers, as found by Europe PMC text mining. Sharing a sentence is not in itself a finding about the gene and the disease. The quoted sentences say what the papers report.
leukodystrophy (6 papers, 2018 to 2024). Leukodystrophies are a group of rare, progressive, metabolic, genetic diseases that affect the brain, spinal cord and often the peripheral nerves. "It is interesting to note that biallelic variants of the cytoplasmic arginine aminoacyl-tRNA synthetase (RARS1) are associated with a hypomyelinating leukodystrophy." (PMID 37179550, 2023). "Two patients with hypomyelinating leukodystrophy were found to have RARS1 biallelic variants (Patient 1: c.1535G>A (p.Arg512Gln) and c.1382G>A (p.Arg461His); Patient 2: homozygous variants c.5A>T (p.Asp2Val))." (PMID 37186453, 2023). "This has also been described in severe forms of RARS1-associated disease, another hypomyelinating leukodystrophy resembling Pelizaeus–Merzbacher-like disease." (PMID 34415310, 2021). "Biallelic RARS1 variants have been linked to hypomyelination leukodystrophy in 30 cases." (PMID 38618971, 2024). "Biallelic variants of RARS1, a gene that encodes the cytoplasmic tRNA synthetase for arginine (ArgRS), are associated with central nervous system (CNS) manifestations, such as hypomyelinating leukodystrophy‐9 and developmental and epileptic encephalopathy (DEE)." (PMID 37186453, 2023). "Patients with RARS1 biallelic mutations frequently exhibit DEE, a severe phenotype, along with hypomyelinating leukodystrophy." (PMID 37186453, 2023). "Furthermore, brain MRI examination in these patients with RARS1‐related DEE may indicate both hypomyelinating leukodystrophy and MCD." (PMID 37186453, 2023).
hepatocellular carcinoma (4 papers, 2022 to 2026). A malignant tumor that arises from hepatocytes. "Together, these results indicate that AH-6809 acts as a potential inhibitor of RARS1, effectively suppressing hepatocellular carcinoma cell proliferation, migration, and invasion, thereby highlighting its therapeutic potential in targeting RARS1-driven tumor progression." (PMID 41451236, 2025). "In hepatocellular carcinoma (HCC), a novel prognostic signature composed of 6 key lactate metabolism-related genes (FKTN, PDSS1, PET117, PUS1, RARS1, and RNASEH1) was developed to predict the survival and tumor microenvironment of HCC patients." (PMID 38529390, 2024). "In hepatocellular carcinoma (HCC), transcriptomic data revealed a lactate metabolism-related gene signature (LMRGS) based on the expression of six genes (FKTN, PDSS1, PET117, PS1, RARS1, and RNASEH1)." (PMID 36713558, 2022).
microcephaly (2 papers, 2023 to 2024). A congenital or acquired developmental disorder in which the circumference of the head is smaller than normal for the person's age and sex. "Compared to patients without epilepsy, those with RARS1‐related epilepsy were more likely to have microcephaly, cerebral atrophy, and speech absence, but less likely to be able to walk independently (P < 0.05)." (PMID 37186453, 2023).
nasopharyngeal carcinoma (2 papers, 2021 to 2022). A carcinoma arising from the nasopharyngeal epithelium. "RARS1 fusion with MAD1L1 has been reported to stimulate the FUBP1/c-Myc signaling pathway, inducing tumorigenesis in nasopharyngeal carcinoma." (PMID 35047511, 2021).
Brain atrophy (1 paper, 2024). Partial or complete wasting (loss) of brain tissue that was once present. "Pathogenic variants in RARS1 decrease ArgRS activity and cause a wide range of symptoms, from severe, early onset epileptic encephalopathy with brain atrophy to a mild condition with relatively maintained myelination." (PMID 38618971, 2024).
liver cancer (1 paper, 2022). An epithelial or non-epithelial malignant neoplasm that arises from the liver. "It is possible that the Neanderthal haplotype may impact expression of RARS1 in liver cancer." (PMID 36503519, 2022). "However, expression of RARS1 is similar in liver cancer patients with Neanderthal introgression compared to liver cancer patients without Neanderthal introgression in this gene." (PMID 36503519, 2022). "The two other genes, RARS1 and RNH1, have shown to be involved in other cancers, but not explicitly liver cancer." (PMID 36503519, 2022).
pituitary adenomas (1 paper, 2022). "RARS1, arginyl-tRNA synthetase 1, plays a role in protein synthesis and higher expression of this gene was observed in pituitary adenomas compared to normal pituitary." (PMID 36503519, 2022).
cancer (6 papers, 2012 to 2025). A tumor composed of atypical neoplastic, often pleomorphic cells that invade other tissues. "Recent studies have increasingly highlighted the involvement of RARS1 in several malignant tumors, demonstrating its association with key oncogenic processes such as cell proliferation, apoptosis, and metabolic reprogramming." (PMID 41451236, 2025). "Single-cell RNA sequencing and spatial transcriptomics further revealed that RARS1 positively regulates macrophage polarization toward the M2 phenotype, which is associated with immune suppression and cancer progression." (PMID 41451236, 2025). "MARS1 and RARS1 are also associated with unfavorable outcomes in at least three different cancer types (ACC, KIRC, LGG, and MESO for MARS1; HNSC, LIHC, and LUAD for RARS1)." (PMID 33266490, 2020). "KEGG enrichment analysis indicated that RARS1 was closely associated with Focal adhesion, PI3K-AKT signaling, and pathways in cancer." (PMID 41451236, 2025). "Pan-cancer analysis further highlighted that RARS1 is upregulated in various cancer types, reinforcing its potential as a universal oncogene." (PMID 41451236, 2025). "Pan-cancer analysis of TCGA datasets revealed that RARS1 expression was significantly elevated in 17 cancer types, including LIHC." (PMID 41451236, 2025).
tumor (5 papers, 2019 to 2025). "The results revealed significantly higher expression of RARS1 in tumor cells compared to other cell types, indicating its prominent role in the tumor microenvironment." (PMID 41451236, 2025). "Future work will include both male and female cohorts to evaluate potential sex-specific effects on RARS1-mediated tumor biology." (PMID 41451236, 2025). "RARS1 not only serves as a prognostic biomarker for LIHC but also represents a promising therapeutic target for modulating tumor growth and improving immune responses." (PMID 41451236, 2025). "Using the GSCA database and cMAP analysis, we identified AH.6809 as a promising therapeutic agent capable of counteracting the tumor-promoting effects of RARS1." (PMID 41451236, 2025). "Clinical feature analysis indicated that RARS1 expression correlated with T stage, tumor grade, and radiotherapy status in LIHC patients." (PMID 41451236, 2025). "Based on single-cell data, we classified malignant tumor cells into RARS1-positive and RARS1-negative groups and analyzed their communication strength and frequency with other cells." (PMID 41451236, 2025). "To explore the role of RARS1 in the LIHC tumor microenvironment, we analyzed immune infiltration in the TCGA LIHC cohort using the ssGSEA algorithm provided by the GSVA package." (PMID 41451236, 2025). "Both in vitro assays, including colony formation and scratch wound healing, as well as in vivo tumor xenograft models, showed a reduction in tumor growth and volume upon RARS1 suppression." (PMID 41451236, 2025). "Single-cell RNA sequencing analysis demonstrated that RARS1 was predominantly expressed in malignant tumor cells." (PMID 41451236, 2025). "RARS1-positive cells exhibited enhanced communication with immune cells, especially M2 macrophages, which are known to promote tumor progression and immune evasion." (PMID 41451236, 2025). "In vivo subcutaneous tumor xenograft models showed that tumors in the RARS1 knockdown group were significantly smaller and lighter than those in the control group." (PMID 41451236, 2025). "Single-cell RNA sequencing analysis revealed that RARS1 is predominantly expressed in malignant tumor cells, with its expression being significantly higher in these cells compared to normal liver cells." (PMID 41451236, 2025). "To experimentally model this phenomenon, we established a THP-1 polarization system using tumor-conditioned media (TCM) derived from either control (NC) or RARS1-knockdown (Sh1) SKHep1 cells." (PMID 41451236, 2025). "Together, these data demonstrate that RARS1-expressing tumor cells orchestrate macrophage polarization toward an immunosuppressive, M2-like state, whereas the loss of RARS1 disrupts this crosstalk and promotes a shift toward a proinflammatory, antitumor macrophage phenotype." (PMID 41451236, 2025). "Cell cycle analysis revealed that RARS1 suppression arrested tumor cells at the G0/G1 phase." (PMID 41451236, 2025). "Furthermore, RARS1-positive cells likely secrete stronger signaling molecules, influencing the tumor immune microenvironment." (PMID 41451236, 2025). "Paired sample analysis confirmed that RARS1 was markedly upregulated in LIHC tumor tissues." (PMID 41451236, 2025). "Tissue microarray staining further confirmed elevated RARS1 expression in tumor samples." (PMID 41451236, 2025). "Moreover, high RARS1 expression was found to be associated with unfavorable clinical features, such as advanced TNM stage and poor tumor differentiation." (PMID 41451236, 2025). "Western blot and RT-PCR analyses demonstrated that RARS1 protein and mRNA levels were significantly upregulated in LIHC tumor tissues." (PMID 41451236, 2025). "Western blot analysis showed that RARS1 knockdown reduced PI3K and phosphorylat-AKT(p-AKT) levels, while increasing GSK3β expression, suggesting that RARS1 modulates the PI3K/p-AKT/GSK3β signaling pathway in tumor proliferation and migration." (PMID 41451236, 2025).
tumor (continued). "This suggests that RARS1 may protect LIHC cells from ferroptosis through its regulation of ENO1 activity, thereby contributing to tumor cell survival." (PMID 41451236, 2025).
infection (1 paper, 2016). The state of being infected such as from the introduction of a foreign agent such as serum, vaccine, antigenic substance or organism. "Quite the contrary, many clones targeting genes required for translation, including those encoding aminoacyl-tRNA synthetases (hars-1, lars-1, rars-1, tars-1, wars-1) and eIF subunits, were required for expression of nlp-29 after infection." (PMID 27129311, 2016).
RARS1 also shares sentences with these, for which no sentence is quoted: breast carcinoma (2 papers); neurologic disorders (2); Ataxia (1); autism (1); Cerebral atrophy (1); Charcot-Marie-Tooth disease (1); developmental and epileptic encephalopathy (1); diseases of the central nervous system (1); Encephalopathy (1); epilepsy (1); glomerulonephritis (1); GM2 gangliosidosis (1); insomnia (1); Leukoencephalopathy (1); melanoma (1); renal diseases (1); trichothiodystrophy (1).